CCND1 (cyclin D1)
Diseases named in the same sentence as CCND1 in open-access papers (continued):
Sharing a sentence is not in itself a finding about the gene and the disease.
tumor (continued). "Secondly, this approach should, theoretically, maintain tumor immunogenicity though blocking immune evasive transcriptional programs associated with upregulation of Cyclin D1 in BRAFi+MEKi resistant cells." (PMID 35444175, 2022). "In our study, Cyclin D1 high expression was significantly associated with the well-differentiated tumor, advanced tumor extent, nodal and distant metastasis, lymphovascular invasion, and pathological stage." (PMID 36532636, 2022). "Some study indicated that low expression of Cyclin D1 was linked to large tumor size, high nuclear grade, and poor prognosis of ccRCC patients." (PMID 34975298, 2022). "In a prior in vitro study, restoration of miR-16 levels was shown to inhibit tumor cell proliferation, linked to the downregulation of Bcl-2 and CCND1." (PMID 35205318, 2022). "In general, overexpression of Cyclin D1 is associated with higher-grade neoplasms and poorer outcomes." (PMID 36136690, 2022). "It has been reported that some miRNAs, differentially expressed by regorafenib treatment, are tumor suppressors associated with decreased expression of cyclin D1 and have an antitumor effect on HCC." (PMID 35163589, 2022). "For example, one group studying HBV-related HCC found a lower level of cyclin D1 expression and a higher frequency of loss of heterozygosity of chromosome 13q in paediatric tumours compared to adult tumours." (PMID 36010647, 2022). "The overexpression/activation of oncogenes or the loss/inactivation of tumor suppressors promotes tumor development and progression via the coordination of D cyclins like cyclin D1 to perform their biological functions." (PMID 35565262, 2022). "These functional alterations were associated with changes in the expression of different tumour markers (CCND1, CDKN2A, etc.; determined by qPCR), which were modulated in a cell‐dependent manner in response of EIF4A3‐silencing." (PMID 36419260, 2022). "STAT1 acts as a tumour suppressor in a range of cancer types and is associated with the expression of Bcl-xL and cyclin D1." (PMID 35781872, 2022). "Emerging evidence suggests that CCND1 amplification is associated with tumor immunosuppression and inhibition of anti-tumor immune effector cells across multiple cancer types." (PMID 35844619, 2022). "Deregulation of the Wnt/β-catenin pathway resulting in neoplastic transformation and tumor progression is associated with overexpression of target genes, such as c-Myc or cyclin D1." (PMID 35406521, 2022). "Most immune checkpoints, especially Cyclin D1, are positively associated with he regulation of tumor proliferation, influencing the cell cycle." (PMID 36358792, 2022). "CCND1 rs9344 was associated with tumor size, however an association resulted in loss of significance after Bonferroni correction." (PMID 34441352, 2021). "Case 10S was extremely instable with an instability index of 68.8 yet maintaining a gain of CCND1 accompanied by a loss of CDH1 in essentially all cells of the tumor." (PMID 34282768, 2021). "Overexpression of cyclin D1 in various human cancers has been regarded as a key mechanism underlying tumor growth, angiogenesis, progression, and metastasis." (PMID 34298825, 2021). "CCND1 is not only a marker of proliferation and tumour growth, but is also associated with metastatic potential." (PMID 34503211, 2021). "Expression of miR-193b was inversely associated with cyclin D1-encoding gene (CCND1) expression in PC cell lines and tumor xenografts." (PMID 34439268, 2021).
tumor (continued). "Taken together—greater expression in primary tumor vs. distant metastases and association with Breslow thickness—these data seem to indicate that CCND1/cyclin D1 upregulation is especially influential in the local growth and expansion of the tumor." (PMID 33804108, 2021). "It was also observed that the therapeutic response was independent of the nuclear expression of RB1, Ki-67 index, p16 loss, or CCND1 amplification in the tumour tissue." (PMID 34068388, 2021). "In particular, since USP2 modulates the stability of critical tumor-associated proteins such as cyclin D1, Mdm2, and FASN, great efforts have been made to establish a USP2-targeting anticancer drug." (PMID 33530560, 2021). "Cyclin D1 overexpression specifically decreased the proliferation of cells lacking BRCA1 or BRCA2, consistent with the mutual exclusivity of BRCA1/2 mutations and CCND1 amplification in tumours." (PMID 34389725, 2021). "The authors reported that high protein expression of fibronectin, cyclin D1, and tumor grade were associated with lymph node involvement." (PMID 34485158, 2021). "It is well documented that decreased PCNA and CCND1 expression is associated with retarded proliferation of tumor cells and that reduced MMP9 and Vimentin expression is closely related to slowed invasion of cancer cells." (PMID 34511432, 2021). "The proteins encoded by STAT3 target genes subsequently precipitated tumor proliferation (such as cyclin D1, BCL-xL)." (PMID 34712264, 2021). "FGFRs, FGFs, and CCND1 methylation differed significantly between tumor and normal adjacent tissue and was associated with HPV and gene amplification status." (PMID 34933671, 2021). "One study (n = 43 participants) showed d-limonene concentrated in breast tissue (mean 41.3 μg/g tissue) and reduction in tumor cyclin D1 expression, which is associated with tumor proliferation arrest." (PMID 34362338, 2021). "Previous studies have indicated that cyclin D1 overexpression occurred early in the oral tumorigenesis process and was significantly associated with advanced tumor stages." (PMID 34281233, 2021). "As a transcription factor, ETS2 is responsible for the transcriptional regulation of a variety of tumor-associated genes, such as Cyclin D1." (PMID 34261460, 2021). "The c-Myc, a critical oncoprotein which collaborates with various growth factors, Ras, and PI3K/Akt through coordination in regulating both cyclin D1 and cyclin E expressions, is implicated in enhancing tumor formation and driving aggressiveness of tumors." (PMID 32630532, 2020). "The overexpression of CCND1 can cause a variety of tumors, increasing tumor cell proliferation, and affecting the prognosis of cancer patients." (PMID 32020871, 2020). "STAT-3 activation can also be linked with proliferation of tumor cells, becauseit induces the expression of cyclin D1 (Masudaet al., 2002)." (PMID 32167126, 2020). "The overexpression of cytoplasmic CCND1 is also reported to be associated with the tumor invasive capability." (PMID 32566661, 2020). "Cyclin D1 overexpression was also found in papillary micro carcinomas that was strongly associated with increased tumor aggressiveness, lymph node metastases, and cell proliferation." (PMID 32198408, 2020). "High levels of fibronectin and cyclin D1 were associated with poor survival (p = 0.018), and with markers of tumour aggressiveness." (PMID 32037399, 2020). "Cyclin D1 is known for its role in the nucleus, but recent clinical studies associate the amount located in the cytoplasmic membrane with tumor invasion and metastasis." (PMID 33317149, 2020). "Loss of control at the G1-to-S transition is a hallmark of tumor development, and aberrant cyclin D1 expression is reported in many human cancers." (PMID 32700164, 2020).
tumor (continued). "The strong association of fibronectin and cyclin D1 with characteristics of tumour aggressiveness such as higher FIGO stage and grade and poorer DSS suggests their clinical relevance." (PMID 32037399, 2020). "The expression of cyclin D1 was also found in the connective tissues, indicating invasion of the tumor cells into the underlying tissues." (PMID 32104177, 2020). "Hyperphosphorylation of RB inactivates its role as a tumor suppressor gene, so mutations targeting CCND1 or RB1 are of great significance for tumor proliferation." (PMID 32318558, 2020). "As indicated by BrdU incorporation and supported by immunoblots of the mitosis-associated signaling molecules, protein kinase B (AKT) and cyclin D1, steatosis enhanced the capacity of lipids to promote tumor growth." (PMID 32879136, 2020). "In most human tumors, the G1/S checkpoint is lost, for example, by loss of pRB or the CDK inhibitor p16INK4A, or by overexpression of cyclin D1 and insensitivity to antigrowth signals is a hallmark of tumor cells." (PMID 32820027, 2020). "Conversely, the restoration of SHP2 reversed the Cyclin D1 decrease and cell cycle defects, and rescued the cell proliferation arrest in vitro and the tumor growth inhibition in vivo caused by SHP2 knockout." (PMID 32944401, 2020). "In summary, targeting PLK1 lead to a striking tumour regression in three out of fpur CCND1-driven PDX models, while AKT1 and mTOR mutated PDX preferably responded to AKT1 and mTOR inhibitors." (PMID 32792481, 2020). "There was also an insignificant association of Ki- 67 (p = 0.22) and Cyclin D1 (p= 0.36) when compared with various involved locations of primary tumours." (PMID 31983161, 2020). "Specifically, tumor-associated microglia (TAM) in tumors from Cyclin D1 and CDK4 knockout mice show a cell morphology characterized by multiple protrusions associated with a reduced state of activation." (PMID 33317149, 2020). "Cyclin D1 is a tumor-associated protooncogene recognized in recent years and overexpression in various tumor cells." (PMID 33101013, 2020). "In our study, we planned to use this alncRNA to inhibit the signaling pathways associated with C-myc and cyclin D1 and tried to suppress tumor proliferation in this way." (PMID 33363214, 2020). "The complex of PKM2/β-catenin is recruited to the promoter of CCND1, which encodes for cyclin D1, leading to cyclin D1 expression and consequently promoting tumor development and tumor cell proliferation." (PMID 33292198, 2020). "Clinical studies have shown a correlation between cyclin D1 expression and tumorigenesis and increased cyclin D1 expression is associated with tumor invasion and metastasis." (PMID 32948740, 2020). "Multi-cytokine responses were inter alia directed against known tumor antigens such as cyclin D1 but also against a (predicted) mutation contained in ERBB3." (PMID 31803175, 2019). "Constitutive activation of β-catenin signaling is involved in the development of human cancers, and overexpression of cyclin D1, c-myc, and c-jun, which are associated with tumor progression." (PMID 30987323, 2019). "It has been reported that both cyclin D1 and cyclin B1 accelerate the cell cycle and are associated with malignance and proliferation of tumor cells 60-63." (PMID 31523191, 2019). "Taken together, these data demonstrate that GR-selective liganding can decrease activating mutant (Y537S) ER tumor growth in association with reduced tumor CCND1 mRNA expression." (PMID 31340854, 2019). "Together, these tumor gene expression data support that SMARCA4 loss results in reduced CCND1 expression in SCCOHT." (PMID 30718512, 2019). "Cyclin D1 overexpression has been shown to be associated with early cancer incidence and tumour progression." (PMID 30793399, 2019). "Overexpression of cyclin D1, a key gene in cell cycle control, is generally associated with many types of tumours, including HCC55." (PMID 31836811, 2019).
tumor (continued). "After adjusting for age, sex, race, and tumor grade, to our surprise, low mRNA level of CCND1 still correlated with a higher risk of death in ccRCC patients." (PMID 31183974, 2019). "Univariate analysis revealed that CCND1 was not only associated with prognosis, but also tumor grade and tumor recurrence." (PMID 31183974, 2019). "CCND1 CN amplification was associated with advanced tumor stage (p = 0.04), a higher grade of tumor differentiation (p < 0.01), LNM (p < 0.01), and alcohol drinking (p = 0.03), but not age, the tumor site, AQ chewing, or cigarette smoking." (PMID 31159251, 2019). "To examine this possible association, we investigated the expression of the downstream proteins, i.e., cyclin D1, c-Myc, and c-Jun, as they are transcriptionally regulated by β-catenin and are implicated in cell cycle control and tumour progression." (PMID 31167387, 2019). "Another 16% showed significant amplifications or increases in mRNA expression of CDK4, CDK6, and/or Cyclin D1 expression; both these classes of mutations would contribute to an aberrantly overactive cell cycle and, presumably, tumor growth." (PMID 29644000, 2018). "With increasing tumor size (median primary tumor size 9.4 cm; range 1.5–35.0) we observed a loss of cyclin D1 (CCND1, p = 0.040) and p21 (CDKN1A, p = 0.037, Mann-Whitney test)." (PMID 29451912, 2018). "Since then, diverse roles for HNF4α have been described, including its ability to function as a tumor suppressor, suppressing several genes (such as cyclin D1, CCND1) known to be causal for HCC initiation, growth, or progression." (PMID 30341289, 2018). "It has been demonstrated that the increased cyclin D1 expression was associated with the malignant transformation in different tumor cell lines, such as lung, liver and prostate." (PMID 29419740, 2018). "Overexpression of MYC and cyclin D1 can cause bypass of cell cycle checkpoints and promote tumor cell proliferation." (PMID 29423038, 2018). "Our findings suggest a novel mechanism through CCND1/E1 promoter derepression by loss/deficiency of SALL2 tumor suppressor function." (PMID 29689621, 2018). "The overexpression and amplification of cyclin D1 contributes to tumor genesis and has been associated with poor prognosis of many cancers of adults, including: esophageal, colon, prostate, pancreas, and bladder cancers." (PMID 29332262, 2018). "Cyclin D1 is a nuclear protein regulating cell cycle progression from the G1 to the S phase and has been implicated in tumor invasion and metastasis in human cancers." (PMID 30428594, 2018). "Due to the limited somatic mutations in each NPC-PDX tumor sample, we incorporated all the SNVs identified in 282 genes as well as CCND1 and CDKN2A to perform pathway analysis (Metacore)." (PMID 30236142, 2018). "The overexpression of cyclin D1 has been associated with worse OS and higher tumor grade in STS of the extremities and retroperitoneum." (PMID 29332262, 2018). "CCND1-deficient mice exhibit the tumor resistance because of the reduced motility and invasiveness of CCND1−/− tumor-associated macrophages." (PMID 28602785, 2017).
tumor (continued). "Fbxo4 is a tumour suppressor, and its tumour suppressing activity has been linked to the dysregulation of cyclin D1 proteolysis." (PMID 29142209, 2017). "Mechanistic studies revealed that G0/G1 arrest and tumor senescence upon pulsed T treatment were associated with a marked decrease in cyclin D1, c-Myc and SKp2, CDK4 and p-Rb levels and upregulation of p27 and p-ERK1/2." (PMID 29371946, 2017). "Expression of MDM2-B is also shown to have tumor promoting activity by causing increased levels of Cyclin D1 and E in vivo." (PMID 28415963, 2017). "Lacking this lncRNA causes cell cycle arrest at the G1/S stage due to decreased cyclin D1 and attenuates tumor growth." (PMID 29199958, 2017). "A high ER receptor content was significantly associated to low tumor grade, low Ki-67 expression, and low levels of cyclins A, B, and E. In contrast, cyclin D1 showed a positive correlation to ER receptor content." (PMID 28528450, 2017). "Myc and cyclin D1 and D2 are important regulators of intestinal stem cells and are implicated in tumor initiation and progression." (PMID 28086833, 2017). "HER1 and HER2 signaling is clearly linked to sustained proliferation of tumor cells, since they up-regulate the expression of Cyclin D1 during most phases of cell cycle." (PMID 29137309, 2017). "Contrasting this, the same variant has also been shown to induce increased expression levels of Cyclin D1 and E, hence, suggesting that this splice variant has a tumor promoting activity in vivo." (PMID 28415963, 2017). "The tumor suppressor function of p16INK4a has been linked to its inhibition of CDK that leads to disassembly of the cyclin D1/CDK complex, thereby resulting in reduced cell proliferation." (PMID 29179500, 2017). "Overexpression of Cyclin D1 in various human cancers is regarded as a key mechanism underlying tumor angiogenesis, progression, and metastasis." (PMID 27854312, 2016). "In the validation set, the A allele of CCND1 SNP rs9344 remained significantly associated with decreased time-to-tumor recurrence." (PMID 26884752, 2016). "We have also shown that forced attachment of Ccnd1 to the membrane (caused by Ccdn1-CAAX expression) induces tumor cell invasiveness and metastasis in tumor cells through a RalB-dependent mechanism." (PMID 27105504, 2016). "Using a combination of cyclin D1 expression, tumor cell differentiation grade, and tumor stages, identifying patients with increased risk of postoperative metastases becomes possible." (PMID 27145270, 2016). "Studies further indicated that cyclin D1 overexpression occurred early in the oral tumorigenesis process and significantly associated with advanced tumor stages." (PMID 27589737, 2016). "Several biomarker candidates like RB expression and localization, Ki-67, p16 loss, and CCND1 (gene encoding cyclin D1) amplification were investigated, but failed, however, to identify a sensitive tumor population." (PMID 27429659, 2016). "Deregulated expression of cyclin D1 is found in a large variety of malignancies and often associated with tumor progression." (PMID 27539223, 2016). "The chimeric cyclin D1-Trop2 protein is implicated in cell transformation; silencing this fusion protein inhibits tumor growth." (PMID 26000093, 2015). "The finding that endogenous expression of cyclin D1b independently promotes transformation of immortalized cells represents a significant advance in our understanding of the differing oncogenic capacity of cyclin D1 variants in tumor biology." (PMID 25787974, 2015). "Clinical evidence suggests that cyclin D1b, a variant of cyclin D1, is associated with tumor progression and poor outcome." (PMID 25787974, 2015).